FAM90A26 (family with sequence similarity 90 member A26)
Synonyms: FAM90A26P
Tractability: No criterion of Open Targets' tractability assessment is met for any kind of drug.
Gene: Protein-coding gene on chromosome 4 (9,170,409 to 9,176,730, forward strand). Ensembl gene ENSG00000229924.
Subcellular location (Human Protein Atlas): Nucleoplasm; Nucleoli
Homologues: Orthologues: chimpanzee FAM90A26 (93% identical), mouse Fam90a1b (29% identical), mouse Fam90a1a (26% identical), rat Fam90a1l1 (25% identical). Paralogues in human: FAM90A3 (95% identical), FAM90A5 (95% identical), FAM90A15 (94% identical), FAM90A16 (94% identical), FAM90A17 (94% identical), FAM90A10 (94% identical), FAM90A13 (94% identical), FAM90A14 (94% identical), FAM90A23 (94% identical), FAM90A9 (94% identical), FAM90A11 (94% identical), FAM90A7 (94% identical), and 9 more.